TRAF3 (TNF receptor associated factor 3)
Diseases named in the same sentence as TRAF3 in open-access papers (continued):
Sharing a sentence is not in itself a finding about the gene and the disease.
multiple myeloma (continued). "Indeed, ablation of TRAF3 in the mouse or reduced TRAF3 levels in myeloma and HSE patients elevate NIK expression resulting in constitutive activation of the NF-κB2 pathway and accumulation of transcriptionally active p52." (PMID 24260396, 2013). "Inactivating mutations and loss of heterozygosity in the TRAF3 locus have been reported in a significant proportion of myeloma patients, suggesting that TRAF3 may function as a tumor suppressor." (PMID 24260396, 2013). "However, p52 levels remained ~twofold higher in LP1 compared to Wt TRAF3-expressing cells, which is consistent with previous observations in myeloma cells and fibroblasts that the presence of LP1 TRAF3 mutant led to higher p52 levels." (PMID 24391649, 2013). "Homozygous deletions and inactivating mutations of the Traf3 gene have been identified in NHL, including splenic marginal zone lymphoma (MZL), B cell chronic lymphocytic leukemia (B-CLL) and mantle cell lymphoma (MCL), as well as multiple myeloma (MM) and Waldenström’s macroglobulinemia (WM)." (PMID 24131623, 2013). "Deletions of NFκB-pathway modulating genes TNFAIP3, BIRC2/BIRC3, TRAF3 or CYLD were identified in 16.6, 4.8, 13.9 and 16.9% of Myeloma XI cases, respectively." (PMID 28584253, 2018). "The non-canonical NF-κB pathway plays an important role in the pathogenesis of multiple myeloma, where it is constitutively activated by recurrent genetic alterations, including NIK amplifications and c-IAP1/2 and TRAF3 deletions." (PMID 28829404, 2017). "TRAF3, a new tumor suppressor identified in human non-Hodgkin lymphoma (NHL) and multiple myeloma (MM), induces PKCδ nuclear translocation in B cells." (PMID 24131623, 2013). "Several studies showed that loss-of-function mutations of TRAF2, TRAF3 or cIAP1/2 protects NIK from proteasomal degradation leading to accumulation of NIK and subsequent constitutive noncanonical NF-κB activation in multiple myeloma cells." (PMID 24533079, 2014). "In hematopoietic cancer cells such as multiple myeloma and adult T-cell leukemia as well as lung cancer cells, either stabilization of the NIK protein through impaired negative regulation by the TRAF3/TRAF2/cIAP complex or aberrant expression of the NIK mRNA have been reported." (PMID 24533079, 2014). "In line with this notion, we and others have previously demonstrated that TRAF3 mediates the anti-proliferative effects of CD40 and LTβR in transformed cell lines and that overexpressed TRAF3 inhibits the growth of carcinoma and myeloma cells." (PMID 24260396, 2013). "Interestingly, a number of genetic alterations promoting NIK stabilization and p100 processing, such as c-IAP1/2 and TRAF3 deletions and NIK amplifications, have been reported in multiple myeloma, where they drive constitutive NF-κB activation and multiple myeloma cell survival." (PMID 28829404, 2017).
B-cell lymphoma (17 papers, 2015 to 2025). "A tumor necrosis factor receptor-associated factor 3 (TRAF3) serves as a tumor suppressor in B-cell lymphoma; nevertheless, it is required for the cell proliferation of anaplastic large T-cell lymphoma by activating the PI3K/AKT and JAK/STAT pathways." (PMID 39176397, 2024). "Chemo-resistant TRAF3-deficient B-cell lymphomas were sensitized to chemotherapeutic drugs by blocking IAP activity using IAP antagonist." (PMID 37679334, 2023). "To determine the relevance of these findings for TRAF3 deficiency in human B cells, we analyzed four human B cell lymphoma-derived cell lines." (PMID 27752131, 2016). "A recent study, inspired by TRAF3 mutations in canine B-cell lymphoma RNA-seq showed that TRAF3 loss resulting in decreased gene expression is a feature of some human DLBCLs." (PMID 26377837, 2015). "A recent lymphoma study in dogs identified a gene (TRAF3) as being commonly mutated in both dog and human B-cell lymphomas." (PMID 26377837, 2015). "TRAF3-deficient B cells exhibit substantially enhanced survival, which in mice results in marked lymphoid organ enlargement, production of autoantibodies, and development of B cell lymphomas (BCL) with age." (PMID 40773231, 2025). "Taken together, we suggest that IAP antagonist plus chemotherapeutics may be more effective in treating TRAF2 or TRAF3 deficient B cell lymphomas." (PMID 37679334, 2023). "We also tested another human B cell lymphoma, Ly7, which has TRAF3 loss." (PMID 37679334, 2023). "In accordance with the notion that the alternative NFκB pathway and therefore also TRAF2 and TRAF3 act as tumor suppressors in B-cells, mice with B-cells deficient in TRAF3 expression demonstrate prolonged B-cell survival and develop spontaneous B-cell lymphoma at a higher age." (PMID 36011046, 2022). "Assuming that in humans TRAF2 and TRAF3 mutations occur in premalignant cells, they may contribute to the initiation of B cell lymphomas through a similar RelB-dependent mechanism as we describe here for LMP1/CD40 mice." (PMID 36110848, 2022). "In addition to these findings, multiple somatic point mutations were identified in canine B-cell lymphoma including TRAF3, POT1, LMNB1 and MVB12A19–21." (PMID 35332215, 2022). "Interestingly, Pim2 is overexpressed in multiple human cancer types, including the B cell malignancies most frequently associated with TRAF3 deficiency—multiple myeloma (MM) and B cell lymphoma (BCL)." (PMID 30319624, 2018). "Several studies have investigated the tumor-suppressive functions of TRAF3, including in B cell lymphoma and head and neck cancers." (PMID 39932808, 2025). "It has been previously reported that LMP1 sequesters and binds TRAF3 more effectively than CD40 to regulate the NF-κB pathway in B-cell lymphoma cells." (PMID 39164228, 2024). "Genetic alterations of TRAF2 or TRAF3 are observed in subsets of human B-cell lymphomas and B cell-specific deletion of TRAF3 led to lymphoma development in aged mice." (PMID 37679334, 2023). "Researchers have identified frequent deletions or mutations of TRAF3 in human B-cell malignancies, and found that B cell-specific deletion of TRAF3 in mice significantly raised the incidence of B-cell lymphoma." (PMID 37798663, 2023). "It is noteworthy that many of the B cell lymphomas arising in the TRAF3/BCL2 double-tg mice show a nuclear localization of TRAF3." (PMID 30687320, 2018). "TRAF2 deficiency in B cells also resulted in elevated NF-κB2 activation; however, TRAF2 and TRAF3 may play opposite roles in regulating NF-κB1 activation that is important for human B cell lymphoma survival and proliferation." (PMID 37679334, 2023). "Our studies provide insight into mechanisms modulating DNA damage-induced apoptosis and may help to develop more effective treatment for TRAF2 or TRAF3 mutant B-cell lymphomas using IAP antagonists." (PMID 37679334, 2023). "The top most significantly mutated genes in B-cell lymphomas are POT1, FBXW7, and TRAF3." (PMID 26377837, 2015).
B-cell lymphoma (continued). "In this report, we show that TRAF3 and BCL2 cooperate to promote development of a variety of mature B cell lymphomas arising from antigen-challenged B cells." (PMID 30687320, 2018). "Human B cell lymphoma (BCL) cell lines also display an inverse correlation between Glut1 and TRAF3 expression, and cell lines with relatively lower TRAF3 expressed show increased sensitivity to glucose deprivation." (PMID 30319624, 2018). "Mice lacking TRAF3 specifically in B cells have autoimmune manifestations, lymphadenopathy, and increased incidence of B cell lymphomas." (PMID 40773231, 2025). "IAP antagonists sensitized chemo-resistant B-cell lymphomas to chemotherapeutic drugs in the absence of TRAF3." (PMID 37679334, 2023).
lymphoma (16 papers, 2013 to 2024). A malignant (clonal) proliferation of B- lymphocytes or T- lymphocytes which involves the lymph nodes, bone marrow and/or extranodal sites. "Overall, we conclude that TRAF3 deficiency rendered lymphoma cells more sensitive to IAP antagonist treatment." (PMID 37679334, 2023). "Ara-C treatment (100 μg/ml) caused a low level of cell death in Ly7 (TRAF3-loss) lymphoma (∼8%), albeit higher than in Ly1 (TRAF3-WT) lymphoma." (PMID 37679334, 2023). "In this regard, we found that human lymphoma cells that either contain TRAF3 loss (Ly-7) or have TRAF3 deleted (Ly-1-TRAF3-KO) were more sensitive to IAP antagonist treatment than their TRAF3 WT controls." (PMID 37679334, 2023). "Thus, a significant mechanism of lymphoma development in dogs caused by TRAF3 and POT1 mutations pivotally requires further study." (PMID 39176397, 2024). "Further elucidating the role of TRAF2 and TRAF3 deficiency in B cell lymphomagenesis may help sensitizing these mutant lymphomas to chemotherapeutic drugs or other therapeutics." (PMID 37679334, 2023). "Importantly, TRAF3-KO Ly1-57 lymphoma was significantly more sensitive to AZD treatment; moreover, combined treatment of AZD and DOX caused a significantly higher level of cell death in TRAF3-KO Ly1-57 lymphoma than its WT counterpart." (PMID 37679334, 2023). "In support of this important impact of TRAF3 deficiency upon the pre-malignant cell phenotype, both functional and genetic loss of TRAF3 have been reported in B cell malignancies, and mice with a B cell specific TRAF3 deficiency have an increased incidence of lymphomas later in life." (PMID 36291813, 2022). "In contrast, Ly1-57 (TRAF3-KO) clone was significantly more sensitive to AZD treatment compared to Ly1 parental lymphoma." (PMID 37679334, 2023). "Overall, we suggest that deficiency in TRAF2 or TRAF3 may confer survival advantage to B cells via elevated NF-κB2 that predisposes B cells to lymphomagenesis by permitting them to accumulate low frequency genetic alterations, other than chromosomal translocations, that eventually cause lymphoma." (PMID 37679334, 2023). "Both Ly1 parental and Ly1-57 (TRAF3-KO) lymphoma cells were insensitive to Ara-C treatment since Ara-C (100μg/ml) caused a minimal level of cell death." (PMID 37679334, 2023). "TRAF3 is a negative regulator of the NF-κB signaling pathway, and the TRAF3 VAF of 8% was consistent with the degree of bone marrow involvement by lymphoma." (PMID 35456397, 2022). "B cell-specific KO of the Traf3 gene in mice leads to increased B cell numbers and spontaneous lymphomas." (PMID 33185187, 2020). "We previously showed that premalignant TRAF3-/- B cells and TRAF3-/- B lymphomas have decreased nuclear levels of PKCδ." (PMID 24131623, 2013). "We also included the study of oridonin, an inhibitor of NF-κB2 and NF-κB1 activation, which also exhibits robust in vitro tumoricidal activity on primary TRAF3-/- B lymphomas harvested from diseased B-TRAF3-/- mice." (PMID 24131623, 2013). "TRAF3-KO Ly1-57 lymphomas were more sensitive to DOX treatment compared to TRAF3-WT Ly1 lymphomas." (PMID 37679334, 2023). "Furthermore, AZD treatment sensitized resistant TRAF3-KO Ly1-57 lymphoma to Ara-C-induced cell death." (PMID 37679334, 2023). "The question is why TRAF3-mutant lymphomas are more sensitive to IAP antagonist treatment." (PMID 37679334, 2023). "In the absence of TRAF3, this NF-κB2/XIAP/cIAP2 signaling cascade may constitute an autoregulatory positive feedback loop and TRAF3-mutant lymphoma cells may rely on this feedback mechanism for their survival." (PMID 37679334, 2023). "We next determined whether WT or TRAF3 mutant human lymphomas exhibited differential sensitivity to IAP antagonist and whether IAP antagonist potentiated chemo-induced apoptosis in TRAF3-mutant lymphomas." (PMID 37679334, 2023).
lymphoma (continued). "Finally, allotransplantation of either splenocytes or cell-containing ascites from lymphoma-bearing TRAF3/BCL2 mice into SCID/NOD immunodeficient mice showed efficient transfer of the parental expanded B-cell clones." (PMID 30687320, 2018). "Our data showed that TRAF2-KO, TRAF3-KO, and TRAF2/3-DKO lymphoma cells were more sensitive to AZD treatment alone or to combined treatment of AZD/DOX." (PMID 37679334, 2023). "We treated Ly1 parental (Ly1-P), TRAF2-KO, TRAF3-KO, and TRAF2/3-DKO lymphoma cells with DOX, AZD, or AZD plus DOX." (PMID 37679334, 2023). "In contrast to TRAF3, the POT1 VAF of 51% was discordant with the frequency of lymphoma cells and suggestive of a potential heterozygous germline variant." (PMID 35456397, 2022). "This difference is mainly found in proteins functionally related to each pathology, for example: sCD44, HIF1A, ZMYM3 or PTPRC for CSF + LM in lymphoma and S100A9, TRAF3, KLK3, KLK2, PTPRC, among others, in the case of CSF + LM in leukemia." (PMID 35053611, 2022).
breast carcinoma (14 papers, 2013 to 2026). "In tumor samples, as compared to normal samples, a notable decrease in the expression level of TRAF3 has been observed, implying a potential inhibitory role of TRAF3 in the onset and progression of breast cancer." (PMID 38825674, 2024). "It has been shown that TRAF3 was a target mRNA of miR-29b-3p and interacted with miR-29b-3p to affect ischemia/reperfusion injury and breast cancer." (PMID 33817278, 2020). "It has been shown that AD 198 has anti-tumor activity superior to DOX in breast cancer, ovarian carcinoma and melanoma models, which was recapitulated in our TRAF3-/- mouse B lymphomas." (PMID 24131623, 2013). "Furthermore, TRAF3-expressing breast cancer cells displayed reduced levels of PD-L1 and when co-cultured with PBMCs induced a pro-inflammatory profile with increased CD16-NK cells and higher levels of IFN-γ and TNF-α and lower IL-10 and Tregs in the culture." (PMID 42196397, 2026). "miR-92b can perform multiple functions by regulating multiple target mRNAs, such as suppressing viability and invasion by targeting EZH2 in breast cancer, and attenuate inflammation by affecting the expression of TRAF3 and inhibiting the MKK3-p38 pathway in acute pancreatitis." (PMID 36670839, 2023). "Interestingly, TRAF3 has been reported to be highly expressed and play an important role in human diseases, such as breast cancer, gastric cancer, and cerebral ischemic stroke." (PMID 33817278, 2020). "The TRAF3 silenced by miR-214 contributed to the osteolytic bone metastasis of breast cancer." (PMID 32579175, 2020). "Furthermore, higher TRAF3 expression is positively correlated with extended relapse-free survival (RFS), OS, and distant metastasis-free survival (DMFS) in breast cancer patients." (PMID 38825674, 2024).
lung carcinoma (14 papers, 2012 to 2025). "In recent years, investigators have discovered that the frequency of TRAF3 gene change in lung cancer is about 5.3%, which is closely related to the development and clinical prognosis of lung cancer." (PMID 37798663, 2023). "The USP17/TRAF2/TRAF3 complex acts to stabilize its client proteins, enhancing inflammatory responses and stemness in lung cancer cells." (PMID 35874839, 2022). "USP17 and OTUD3 promote lung cancer stemness through mediating TRAF2/TRAF3 complex and stabilizing GRP78, respectively." (PMID 32549341, 2020). "Expression levels of OTUD7B, NIK and TRAF3 in tissue samples from lung cancer patients were examined by immunohistochemistry." (PMID 33198776, 2020). "Missense mutations at R376 (R376W or Q) located in the linker between the coiled-coil and TRAF-C domains of TRAF3 are detected in six patients with lung cancer, CRC, SSCC, and melanoma (TCGA; COSMIC)." (PMID 30294322, 2018). "Increased USP17 expression disrupted the TRAF2/TRAF3 complex formation and stabilized its target proteins, leading to elevated inflammation, stemness, and transformation ability in lung cancer cells and increased macrophage recruitment into tumors." (PMID 30038267, 2018). "This study provides new insights into the effects and regulating mechanism of TRAF3 on lung adenocarcinoma, which may carry important clinical implications for the personalized treatment of lung cancer." (PMID 37798663, 2023). "Mutations in various upstream regulators (TRAF2, TRAF3, cIAP1&2, CD40) lead to increased stability of NIK and subsequent activation of the noncanonical NF-kB pathway, and this mechanism of activation appears to be important for different cancer types including DLBC and lung cancer." (PMID 34970479, 2021). "TRAF2 forms a complex with TRAF3 that increased TMAs recruitment mediated by USP17, thereby enhancing stemness and inflammation in lung cancer cells." (PMID 37415241, 2023). "However, the role of TRAF3 in lung cancer and its molecular mechanisms remain unclear." (PMID 37798663, 2023). "In brief, OTUD7B deubiquitinates TRAF3 and inhibits NIK to suppress LCL161-induced lung cancer cell invasion and migration." (PMID 33198776, 2020). "To verify the clinical application value of our results, we analysed the expression of OTUD7B, TRAF3 and NIK in 146 lung cancer tissues and their correlation with prognosis." (PMID 33198776, 2020). "Consistently, USP17 expression in lung cancer cells enhanced basal and stimuli-induced inflammatory responses by stabilizing NIK, c-Rel, and IRF5 through disrupting the TRAF2/TRAF3 complex." (PMID 30038267, 2018). "The ATG5-dependency of TRAF3 levels and transcriptional events were also demonstrated by CRISPR-Cas9 deletion of ATG5 in a second RAS-mutant lung cancer line, NCI-H23." (PMID 29146913, 2017). "For instance, OTUD7B functions to prevent TRAF3 degradation in lung cancer cell cells, suppressing their invasiveness though the non-canonical NF-κB pathway." (PMID 39990225, 2025). "In our study, we found that overexpressed OTUD7B inhibits NIK and the non-canonical NF-κB pathway in lung cancer cells by binding to and deubiquitinating TRAF3." (PMID 33198776, 2020). "Furthermore, OTUD7B can inhibit LCL161-induced lung cancer cell invasion and migration by deubiquitinating TRAF3, inhibiting NIK and preventing non-canonical NF-κB activation." (PMID 33198776, 2020). "In addition, knockdown of FLJ20420 expression also significantly increased the expression of PRKCBP2, TGFBR1, TGFB2, CLCN4, TRAF3, MYLK and ACTA2, while decreasing the expression of SMAD5 and prot-LBC, resulting in an increased apoptotic potential in FLJ20420-silenced lung cancer cells." (PMID 22567091, 2012).